VIM (vimentin)
Diseases named in the same sentence as VIM in open-access papers (continued):
Sharing a sentence is not in itself a finding about the gene and the disease.
colorectal cancer (continued). "Vimentin is highly expressed in the stroma of colorectal cancer cells compared to healthy cells, but interestingly, not in the cancer cells themselves." (PMID 25852822, 2015). "Interestingly, in colorectal cancer, a strong positive correlation was observed between the expression of THBS2 and genes encoding the EMT markers N-cadherin, vimentin, TWIST1, and SNAIL, while there was a negative correlation with CDH1." (PMID 39857742, 2025). "Thus using scRNAseq data, we verified that most of the single cells expressing MKI67 and the cells expressing vimentin do not overlap, which suggests that the high proliferation subgroup and mesenchymal subgroup are distinct subgroups in colorectal cancers." (PMID 34256801, 2021). "Though all findings indicate a future significance of vimentin and fibronectin genes for different malignancies with clinical relevance, however, more research will be necessary to particularly assess the major function of these genes in the process of EMT and tumorgenesis in colorectal carcinoma." (PMID 28900381, 2017). "Research on colorectal cancer has demonstrated that β-catenin subsequently increases the expression of EMT-related transcription factors Twist and Snail, along with the upregulation of mesenchymal marker Vimentin and the downregulation of epithelial marker ZO-1." (PMID 27611941, 2016). "Interestingly, we found that some CD133+ cells expressed vimentin but not E-cadherin in 13/20 detected human colorectal cancer tissues." (PMID 26284927, 2015). "We observed that these primary colorectal cancer (CRC) cells lost expression of the E-cadherin epithelial marker, which was instead expressed in cancer and normal colon mucosa of the same patient, while overexpressed vimentin (mesenchymal marker), Twist1, Snail (EMT markers) and COX2." (PMID 25738332, 2015). "F. nucleatum promotes EMT by regulating the expression of E-cadherin, Vimentin, N-cadherin, and Snail1 in noncancerous human immortalized oral epithelial cells and oral squamous cell cancer and by regulating the expression of Snail, E-cadherin, and fibronectin in colorectal cancer." (PMID 35198889, 2022). "Immunohistochemical examination revealed the concurrence of histologically proved GIST (strongly positive staining for c-kit, vimentin, SMA, and focal positive in S-100, while CD-34 was negative) and Dukes Stage C, (T3, N3, M0 according the TNM staging classification of colorectal cancer)." (PMID 17708776, 2007).
ovarian carcinoma (191 papers, 1994 to 2026). A malignant neoplasm originating from the surface ovarian epithelium. "Vimentin has previously been shown to play a central role in EMT-mediated metastasis and targeting vimentin can increase susceptibility to chemotherapy in ovarian cancer cells." (PMID 39285292, 2024). "Our previous studies have also shown a sustained loss of PLEC and vimentin in an OCT4A knockdown HEY ovarian cancer cell line." (PMID 34001250, 2021). "We evaluated the expression of mucin-1 (MUC1), cytokeratin 8/18 (CK 8/18) and Wilms’ tumor 1(WT-1), all diagnostic markers of ovarian cancer, and vimentin and CD44 were also analyzed." (PMID 32392708, 2020). "Multivariate analysis revealed that high levels of Vimentin, Twist expression and lower levels of E-cadherin expression were independent risk factors for poor prognosis of patients with ovarian cancer." (PMID 30819230, 2019). "SIRT6-mediated invasiveness of ovarian cancer cells was associated with the expression of epithelial-to-mesenchymal transition-related signaling molecules such as snail, vimentin, N-cadherin, E-cadherin, and activated β-catenin." (PMID 30524965, 2018). "In our study, we found that linc-ROR was associated with expression of the EMT-associated markers E-cadherin, vimentin, β-catenin, and c-myc in ovarian cancer cells." (PMID 29050257, 2017). "Expression of vimentin has been associated with invasive behavior in both ovarian cancer cell lines and patient ascites." (PMID 28038455, 2017). "Meanwhile, 20(S)-Rg3 caused E-cadherin increase and N-cadherin and vimentin decrease in A2780 ovarian cancer cells and HEC-1-B endometrial cancer cells." (PMID 28881818, 2017). "Collectively, 1α,25(OH)2D3 inhibited the migration of ovarian cancer cells, which was associated with the altered expression of E-cadherin and Vimentin." (PMID 27548154, 2016). "The FBXW7-vimentin association may represent previously unrecognized pathway with therapeutic relevance in ovarian carcinoma." (PMID 41869454, 2026). "Although malignant peritoneal mesothelioma and ovarian carcinoma are barely distinguishable morphologically and share many diagnostic markers such as keratins and vimentin, there are some biological and immunohistochemical differences to distinguish both cancers." (PMID 36873079, 2023). "Therefore, markers, such as OCT3/4, NANOG, and Vimentin, can be used as diagnostic markers for ovarian cancer cell detection." (PMID 33671303, 2021). "We also report for the first time that the suppression of TIMP-2 in ovarian cancer cell lines is associated with a loss of E-Cad mRNA expression with a corresponding increase in the mRNA expression of N-Cad, VIM and a decrease in the mRNA expression of COL12A1." (PMID 33023532, 2020). "Similarly, in ovarian cancer, the presence of a higher percentage of vimentin positive cells in metastatic pleural effusions is associated with increased chemoresistance and poor initial response to chemotherapy." (PMID 27253518, 2016). "However, the role of EMT and MET related events associated with ZEB1, ZEB2, E-cadherin, vimentin and miR-200 family is highly complex, which certainly requires further investigation in the context of endometriosis and ovarian cancer." (PMID 26819681, 2015). "To investigate the role of Vimentin in the promotion of stemness and PARPi resistance in ovarian cancer by KLF5, we conducted Vimentin rescue experiments." (PMID 40307891, 2025). "Our findings suggested that KLF5 played a role in regulating PARPi resistance and stemness of ovarian cancer through the modulation of Vimentin expression." (PMID 40307891, 2025). "KLF5 enhances stemness and contributes to PARPi resistance in ovarian cancer through Vimentin regulation." (PMID 40307891, 2025). "The downregulation of vimentin, one of the main regulators of mechanosensing, has been reported in ovarian cancer cell line models during the acquisition of resistance." (PMID 41399494, 2025).
ovarian carcinoma (continued). "In summary, this study validates that KLF5 increases ovarian cancer cell stemness and induces PARPi resistance by binding to Vimentin and regulating its expression." (PMID 40307891, 2025). "In the present study, the presence of Snail and vimentin in primary and immortalized ovarian cancer cells was detected using immunofluorescence staining." (PMID 38791431, 2024). "Our result demonstrated that both EMT transcription factors (Snail, ZEB1, Twist) and EMT protein markers (Vimentin) were responds to FSH in epithelial ovarian cancer cells." (PMID 38505602, 2024). "Trim56 and Trim16 are considered as ubiquitin ligase for vimentin to suppress ovarian cancer and lung adenocarcinoma progression, respectively." (PMID 38383479, 2024). "The findings of Slug, Vimentin, and N-cadherin expression in A549 cells are entirely similar to the previous data in which Slug, Vimentin, and N-cadherin are expressed in multiple cancers, including breast, pancreatic, colon, and ovarian cancer." (PMID 37528887, 2023). "Inhibition of vimentin by the organic FiVe1 significantly sensitised the ovarian cancer cells towards cisplatin and led to higher rates of apoptosis even in the resistant cancer cells." (PMID 37345897, 2023). "The TRIM56 inhibition of ovarian cancer migration and invasion in vitro occurs via an inhibitory effect on Vimentin." (PMID 36902478, 2023). "This high proportion of cases positive for both E-cadherin and vimentin is also reported in the literature in the serous subtype of ovarian carcinomas." (PMID 37760985, 2023). "Mesenchymal markers such as vimentin/fibronectin/N-cadherin have been reported to be over-expressed either at the genetic level or at the protein level on treating ovarian cancer cells or cell lines in various studies." (PMID 36766756, 2023). "Vimentin is expressed in normal endometrial epithelial cells and has been used to distinguish endometrial cancer from ovarian cancer, illustrating tissue specific differences." (PMID 37146405, 2023). "RPL22L1 can promote ovarian cancer metastasis by inhibiting vimentin and N-cadherin expression, thereby inducing epithelial-mesenchymal transition." (PMID 35513791, 2022). "Recent studies have shown that miR-506 inhibits TGFβ-induced EMT by targeting SNAI2 and suppressing vimentin and N-cadherin expression in ovarian cancer." (PMID 37529006, 2022). "Ovarian cancer cells showed increased expression of E-cadherin and decreased expression of V-cadherin and vimentin." (PMID 36088429, 2022). "Here, we found that the overexpressed ACSM3 blocked the expression of Integrin β1 and p-AKT, leading to the down-regulation of cyclin D1, c-Myc, Vimentin and the up-regulation of E-cadherin in ovarian cancer cells." (PMID 33869039, 2021). "SMYD3 and ITGB6 activated the TGFβ1/Smad3 pathway and then induced the upregulation of Snail, Vimentin and N-cadherin and the downregulation of E-cadherin in 3D-cultured ovarian cancer spheroids." (PMID 34621667, 2021). "In a later proteomics study, we identified and validated that stable knockdown of OCT4A in HEY ovarian cancer cell line and the associated xenografts showed a loss of PLEC and vimentin expression." (PMID 34001250, 2021). "TRPM7 expression was negatively correlated to E-cadherin expression, but positively correlated to Vimentin, N-cadherin, and Twist expression in ovarian cancer." (PMID 34901284, 2021). "In the same study, we showed enhanced expression of PLEC and vimentin in ovarian cancer cell lines after treatments with paclitaxel or cisplatin, which was consistent with increased expression of OCT4A in these cells." (PMID 34001250, 2021). "With this in mind, what is the mechanism of the upregulation of N-cadherin, Snail, and Vimentin and downregulation of E-cadherin during 2D-cultured ovarian cancer cell transformation into 3D spheroids?" (PMID 34621667, 2021). "We have selected and identified thioated aptamers with high specificity for vimentin using human ovarian cancer tissues." (PMID 34770931, 2021).
ovarian carcinoma (continued). "We also demonstrated that the inhibition of vimentin with the recently developed inhibitor FiVe1 led to a significant sensitization of ovarian cancer cells to cisplatin and to a reversal of resistance in the cisplatin-resistant cell line." (PMID 32466394, 2020). "YWHAZ also promotes ovarian cancer metastasis via vimentin‐dependent pathways and the addition of P4 decreased vimentin levels in our experiments." (PMID 32590878, 2020). "Vimentin was identified as a BODIPY-cisplatin binding partner in both ovarian cancer cell lines (spot 1 and 1*)." (PMID 32466394, 2020). "In ovarian cancer cells, the effect of salinomycin on vimentin and EMT was achieved through repression of the Wnt/β-catenin pathway, which also induces EMT and vimentin expression." (PMID 31940801, 2020). "On the whole, these findings are in line with previous data showing that, in ovarian cancer, the ability to form spheroids correlates with the presence of abundant vimentin." (PMID 33250051, 2020). "Further studies have shown that in ovarian cancer cells, the increased expression of βII- and βIII tubulin isotypes induces resistance to laulimalide, as does the downregulation of vimentin expression in human ovarian carcinoma cells." (PMID 33371188, 2020). "In ovarian cancer cells, Trim56 has been found to be the ubiquitin ligase for Vimentin and suppress tumor invasion and migration." (PMID 33046716, 2020). "According to a previous study, during the EMT process cells gain invasive and migratory behaviors, and accompanying that, vimentin and some MMPs are overexpressed in ovarian cancer." (PMID 31477564, 2019). "TRPM7 expression is negatively correlated with E-cadherin, but positively with N-cadherin, Vimentin and Twist expression in ovarian cancer samples." (PMID 30819230, 2019). "Aim of present study is to investigate promoter methylation of CDH1 and VIM gene and etiology of epithelial ovarian cancer (EOC)." (PMID 31653136, 2019). "The PMCs in tumors from patients with ovarian cancer exhibited lower expression of E-cadherin and higher expression of vimentin than the PMCs in the cancer-free zones of the omentum." (PMID 31086083, 2019). "The expression of TRPM7 and EMT markers (Vimentin, N-cadherin, Twist and E-cadherin) in ovarian cancer samples was detected." (PMID 30819230, 2019). "As TH are able to rapidly induce EMT in ovarian cancer cell lines, as a first approach we decided to investigate the action of T3 on E-cadherin and vimentin expression, two important markers of epithelial and mesenchymal cells, respectively." (PMID 30899247, 2019). "Han X showed that TET1 promotes cisplatin-resistance via demethylating the vimentin promoter in ovarian cancer." (PMID 31656201, 2019). "Further analyses indicated that the levels of TRPM7 expression were negatively correlated with E-cadherin (p = 0.0017), but positively with Vimentin ((p = 0.0107), and Twist (p = 0.0007) in ovarian cancer tissues." (PMID 30819230, 2019). "Decreased expression levels of Oct-4, NOTCH1, and vimentin in quiescent sorted ovarian cancer spheroid cells can be reversibly restored after the quiescent spheroid cells reenter the cell cycle and form new colonies." (PMID 30319732, 2018). "Suppression of EMT by upregulating E-cadherin and downregulating vimentin by genistein in ovarian cancer has been demonstrated which was in agreement with our current data." (PMID 29743815, 2018). "We not only observed an increase in vimentin in the ovarian cancer cells in our study, but further confirmed the EMT induction through increase in another mesenchymal marker, ZEB1, with a simultaneous decrease in the epithelial marker, e-cadherin." (PMID 30131543, 2018). "In contrast, expression of the mesenchymal elements N-cadherin, Slug, and vimentin decreased in ELF3-transfected ovarian cancer cells." (PMID 28199976, 2017).
ovarian carcinoma (continued). "Mir-9 levels are often elevated in ovarian cancer tissues in comparison with normal control tissues and are associated with EMT via targeting of Ecad by miR-9 and consequent enhancement of Ncad and vimentin expression." (PMID 28792442, 2017). "The RT-PCR results showed that the mesenchymal marker (Vimentin) and transcription factor (Snail) were upregulated and epithelial marker (E-cadherin) was downregulated in hypoxia-treatment ovarian cancer cells." (PMID 28878214, 2017). "The over-expression of EGFR was reported to be involved in EMT activation via the Akt/Erk1/2 pathways, inducing Vimentin expression and dowregulation of E-cadherin favoring invasiveness in ovarian cancer cells." (PMID 26910918, 2017). "In the present work, vimentin downregulation was confirmed in cisplatin-resistant ovarian cancer cell lines A2780-DR and HO-8910 compared to their respective drug-sensitive controls." (PMID 27322682, 2016). "We found that expression of both E-cadherin and Vimentin were observed in human ovarian cancer SKOV-3 cells." (PMID 27548154, 2016). "Taken together, we demonstrated that vimentin silencing enhanced cells' resistance to cisplatin via prolonged G2 arrest and increased exocytosis, suggesting that vimentin is a potential target for treatment of drug resistant ovarian cancer." (PMID 27322682, 2016). "Overexpression of TET3 reversed TGF-β1-induced EMT phenotypes including the expression pattern of molecular markers (E-cadherin, Vimentin, N-cadherin, Snail) and migratory and invasive capabilities of ovarian cancer cells." (PMID 27141829, 2016). "Our previous study showed that vimentin was downregulated in drug resistant ovarian cancer cell line A2780-DR." (PMID 27322682, 2016). "This demonstrated that the low expression of vimentin positively correlates with the low proliferation rates of ovarian cancer cells." (PMID 27322682, 2016). "Downregulation of vimentin was identified in widely used drug resistant ovarian cancer cell lines in the present and previous studies, suggesting that the low expression of vimentin correlated with drug resistance in ovarian cancer cells." (PMID 27322682, 2016). "We found all three ascites from ovarian cancer patients reduced the expression of an epithelial marker (E-cadherin), and increased the expression of mesenchymal markers (Snail and Vimentin) and these changes were statistically significant." (PMID 27825119, 2016). "Our data proposed a new mechanism underlying vimentin-mediated cisplatin resistance and suggested that vimentin was a new therapeutic target for treating drug-resistant ovarian cancer." (PMID 27322682, 2016). "In contrast, miR-506, a new class of miRNA, suppresses EMT and metastasis in ovarian cancer by regulating both E-cadherin and Vimentin/N-cadherin." (PMID 27612152, 2016). "In the present study, we found that the expression of vimentin was downregulated in drug-resistant ovarian cancer cell lines A2780-DR and HO-8910 as compared to their respective control cells." (PMID 27322682, 2016). "Downregulation of vimentin was also found in ovarian cancer cells resistant to peloruside A and laulimalide." (PMID 27322682, 2016). "Taken together, our results demonstrate that vimentin silencing in ovarian cancer cells upregulates proteins of the exocytotic process to decrease cellular cisplatin accumulation." (PMID 27322682, 2016). "Conversely, the incubation of A2780-derived, SKOV3-derived, or primary ovarian cancer derived NCSLCs with rhCCL5 decreased the level of the epithelial marker E-cadherin and increased the level of the mesenchymal markers vimentin and snail." (PMID 25788271, 2015). "In cervical and ovarian cancers, the number of cells that express mesenchymal marker vimentin is inversely related to RCAS1 expression, as remodeling of stromal tissue by vimentin results in tumor invasion and metastasis." (PMID 24885040, 2014).